PIAS1 (protein inhibitor of activated STAT 1)
Diseases named in the same sentence as PIAS1 in open-access papers (continued):
Sharing a sentence is not in itself a finding about the gene and the disease.
breast carcinoma (continued). "Indeed, STAT1 inhibitors SOCS1 and SHP1/2 (component of PTPs) are also commonly hyperactivated in breast cancer, and elevated expression of PIAS1 has been observed in prostate and breast cancers." (PMID 31658669, 2019). "In breast cancer, PIAS1 regulates tumourigenesis through gene silencing and may serve as a potential survival biomarker." (PMID 31639157, 2019). "Interestingly, the protein abundance and nuclear localization of PIAS1 were found to predict positive outcome in a cohort of breast cancer patients suggesting potential utility of these two PIAS1 parameters as prognostic biomarkers in breast cancer." (PMID 30096838, 2018). "Thus, AQUA and HALO-based analyses suggest that the protein abundance and subcellular localization of PIAS1 in the TMA correlated with breast cancer patient DSOS." (PMID 28493978, 2017). "Thus, it would be interesting to evaluate the contribution of other PIAS1 SUMO substrates in its potential ability to regulate breast cancer invasiveness and metastasis, and to its utility as a biomarker in breast cancer." (PMID 28493978, 2017). "Reference material comprised human breast cancer MDA-MB-231 cells where the abundance of endogenous PIAS1 was decreased by PIAS1 RNAi knockdown (samples 1 and 2), left unchanged (sample 3), or increased by overexpression (sample 4) to provide increasing cellular concentrations of PIAS1." (PMID 28493978, 2017). "PIAS1 has also been suggested to promote breast cancer cell apoptosis." (PMID 28493978, 2017). "The findings that the protein abundance or nuclear localization of PIAS1 correlates with breast cancer patient survival led us next to determine the mechanism by which PIAS1 might regulate the malignant behaviour of breast cancer cells." (PMID 28493978, 2017). "PIAS1 suppresses the malignant behaviour human breast cancer cells in organoid cultures." (PMID 28493978, 2017). "TGFβ reduces the abundance of E-cadherin and PIAS1 in breast cancer cell-derived organoids." (PMID 25594015, 2014). "Elevated PIAS1 expression was observed in breast cancer patient samples." (PMID 24586797, 2014). "Targeting the PIAS1 epigenetic pathway may represent a novel therapeutic strategy for the treatment of breast cancer." (PMID 24586797, 2014). "It is possible that the PIAS1 epigenetic pathway may provide a link between inflammation and the development of breast cancer." (PMID 24586797, 2014). "PIAS1 knockdown in breast cancer cells inhibited tumor growth in vivo." (PMID 24586797, 2014). "In gain of function studies, we find that PIAS1 acts in a SUMO E3 ligase-dependent manner to suppress the ability of TGFβ to promote activation of the matrix metalloproteinase 2 (MMP2) and associated invasive behavior of breast cancer cells." (PMID 25594015, 2014). "Correlating with the ability of PIAS1 to suppress breast cancer invasiveness and metastasis, PIAS1 inhibits TGFβ-induced activation of the matrix metalloproteinase MMP2 as well as the induction of outgrowths from MDA-MB-231 breast cancer cell-derived organoids." (PMID 25594015, 2014). "Importantly, inhibition of the SUMO E3-ligase activity of PIAS1 in breast cancer cells promotes metastases in mice in vivo." (PMID 25594015, 2014). "Microarray analysis of PIAS1 knockdown breast cancer cells has uncovered an essential role of PIAS1 in the suppression of a group of genes previously known to be clinically relevant to breast cancer, such as WNT5A." (PMID 24586797, 2014). "Finally, disruption of the SUMO E3 ligase activity of PIAS1 in MDA-MB-231 breast cancer cells enhances the rate of development of bone metastasis in mice following intracardiac injection of the breast cancer cells." (PMID 25594015, 2014). "PIAS1 acts by delineating histone modifications and DNA methylation to silence the expression of a subset of clinically relevant genes, including breast cancer DNA methylation signature genes such as cyclin D2 and estrogen receptor, and breast tumor suppressor WNT5A." (PMID 24586797, 2014).
breast carcinoma (continued). "PIAS1 represents a cell-autonomous mechanism that regulates TGFβ-induced breast cancer progression." (PMID 25594015, 2014). "We next determined the role of PIAS1 in the invasive behavior of breast cancer cells." (PMID 25594015, 2014). "Thus, PIAS1 can both upregulate and downregulate ERα activity in breast cancer." (PMID 34503213, 2021). "In addition, our findings suggest that PIAS1-SnoN sumoylation pathway may play a crucial role in suppression of the invasive growth of breast cancer cell-derived organoids." (PMID 28493978, 2017). "Therefore, we asked whether PIAS1 suppresses the invasive behaviour of breast cancer cells via SnoN sumoylation." (PMID 28493978, 2017). "Collectively, our findings suggest the PIAS1-SnoN sumoylation pathway may play a fundamental role in suppression of human breast cancer invasiveness and potentially metastasis, and identify PIAS1 as a biomarker that predicts improved survival of breast cancer patients." (PMID 28493978, 2017). "However, the relevance of PIAS1 in human cancer and mechanisms by which PIAS1 might regulate breast cancer metastasis remain to be elucidated." (PMID 28493978, 2017). "We explored whether the PIAS1 epigenetic pathway also operates in breast cancer cells." (PMID 24586797, 2014). "The finding that PIAS1 knockdown affects breast cancer cell survival specifically under the conditions that favor stem cell growth suggests a possibility that PIAS1 may play a role in the regulation of breast cancer stem cells/tumor-initiating cells (TICs)." (PMID 24586797, 2014). "In future studies, it will be also important to determine whether PIAS1 function intersects with other regulators of breast cancer metastasis including the transcriptional regulators Zeb1/2 and Twist, which are both induced by TGFβ signaling and promote tumor metastasis." (PMID 25594015, 2014). "The novel finding that PIAS1 acts in a SUMO E3 ligase-dependent manner to suppress TGFβ-induced breast cancer cell invasiveness using cellular, molecular, and organoid readouts raised the fundamental question of whether PIAS1 might regulate breast cancer metastasis in vivo." (PMID 25594015, 2014). "Thus, inhibition of PIAS3 may be an attractive therapeutic target in HR-positive breast cancer, but although the targeting of PIAS1 in breast cancers overexpressing PIAS1 could potentially relieve PIAS1-mediated epigenetic repression, the role of PIAS1 as a repressor of invasion must be considered." (PMID 34503213, 2021). "It has been shown that the activation of PIAS1 suppresses the ability of TGFβ to activate matrix metalloproteinase 2 (MMP2) and invasive properties of breast cancer cells." (PMID 26905733, 2016). "We have also found that PIAS1 inhibits in a SUMO E3 ligase-dependent manner the ability of TGFβ to promote the disruption and invasive behavior of MDA-MB-231 breast cancer-derived organoids in three-dimensional cultures." (PMID 25594015, 2014). "To investigate the role of the SUMO E3 ligase PIAS1 in the invasive and metastatic behavior of epithelial tumor cells, we used human MDA-MB-231 breast cancer cells." (PMID 25594015, 2014). "The finding that PIAS1 regulates TGFβ-induced MMP2 activation and invasiveness in breast cancer cells led us next to determine the role of PIAS1 in the invasive and metastatic behavior of breast cancer." (PMID 25594015, 2014). "In contrast, expression of a SUMO E3 ligase inactive mutant of PIAS1, owing to replacement of Cysteine 350 with serine (PIAS1 (CS)), enhanced TGFβ-induced activation of MMP2 in MDA-MB-231 breast cancer cells." (PMID 25594015, 2014). "Although previous studies have implicated PIAS1 as a suppressor of TGF-β signaling and EMT in breast cancer, its prognostic relevance in OSCC has not been clearly established." (PMID 40941002, 2025). "Our results demonstrate that PIAS1 is also not involved in DNA repair mechanisms triggered by gamma irradiation as it has been shown in breast cancer." (PMID 31639157, 2019).
breast carcinoma (continued). "In order to promote EMT and invasive growth, data suggest that TGFβ, in turn, reduces the protein abundance of PIAS1 and proportion of SUMOylated SnoN in non-transformed mammary epithelial cells and breast carcinomas." (PMID 30096838, 2018). "Notably, PIAS1 acts in a SUMO E3 ligase-dependent manner to supress the invasive and metastatic growth of breast cancer cells." (PMID 28493978, 2017). "Consistent with the function of PIAS1 in regulating TGFβ-induced MMP2 activation, we found that expression of wild type PIAS1 suppressed the ability of TGFβ to confer an invasive behavior in MDA-MB-231 breast cancer cells." (PMID 25594015, 2014). "The PIAS1 epigenetic pathway is increased in breast cancer and, in addition to silencing genes such as ESR1, also silences the tumor suppressor WNT5A, which has been shown to increase self-renewal of breast tumor initiating cells and requires PIAS1 activity as a SUMO E3 ligase." (PMID 35887358, 2022). "MYC is also overexpressed in one third of breast cancers and PIAS1 is essential for the viability of MYC-dependent breast cancer cells, with reduced proliferation of MYC-dependent MDA-MB-231 cell line observed when PIAS1 is depleted, which is not observed in MYC-independent MCF7 cells." (PMID 35887358, 2022).
prostate carcinoma (14 papers, 2014 to 2025). A carcinoma that arises from epithelial cells of the prostate gland. "Previous studies have shown that PIAS1 is increased in human prostate cancer and promotes tumor cell proliferation by inhibiting cell cycle inhibitors." (PMID 38528630, 2024). "At that time, PIAS1 overexpression was reported for first time in the nucleus of prostate cancer cells." (PMID 38590645, 2024). "The work from Palvimo laboratory revealed that PIAS1 is a chromatin-bound AR coregulator that functions in a target gene selective fashion to regulate prostate cancer cell growth." (PMID 33572160, 2021). "Recent work from the Culig laboratory established PIAS1 as a positive feedback regulator of AR signaling, which is achieved through enhanced AR stabilization in prostate cancer." (PMID 33572160, 2021). "Downregulation of PIAS1 impairs colony formation and proliferation of prostate cancer cells through the p21-dependent cell cycle arrest in the G0/G1 phase." (PMID 33273928, 2020). "PIAS1 overexpression was reported in several cancers, including prostate cancer, multiple myeloma, and B-cell lymphomas." (PMID 32047143, 2020). "PIAS1 has been extensively studied in other cancer lines, such as human prostate cancer, where PIAS1 expression is increased and enhanced proliferation through inhibition of p2121." (PMID 32047143, 2020). "In breast and prostate cancer PIAS1 has been reported to be involved in cancer progression and appears to be a valid target for cancer therapy even in resistant cells." (PMID 31639157, 2019). "On the other hand, PIAS1 has been suggested to predict poor outcome in patients with prostate cancer." (PMID 28493978, 2017). "When PIAS1 was down-regulated, the effect of enzalutamide on inhibition of prostate cancer cells was enhanced." (PMID 29214142, 2017). "Previous studies revealed that PIAS1 is regulated by AR, and its expression is increased in prostate cancer." (PMID 29214142, 2017). "The expression of PIAS1 is substantially higher in prostate cancer than in normal tissues." (PMID 33273928, 2020). "Furthermore, we demonstrate that PIAS1 is a crucial factor for survival of treatment-naïve and docetaxel resistant prostate cancer cells." (PMID 25474038, 2014). "We assessed the potential effect of SUMO3 modification on AR intracellular localization by immunostaining in AR-negative prostate cancer DU145 cells, and detected the effect of PIAS1/SUMO3 overexpression on AR sumoylation related degradation." (PMID 31752909, 2019). "Taken together, these in vitro data demonstrate that PIAS1 is not a promising therapeutic target in UC cancer as previously shown in different entities such as prostate cancer (PCa)." (PMID 31639157, 2019).
viral infection (7 papers, 2019 to 2024). "It will be interesting to explore whether METTL3 and other members of the m6A RNA modification pathway are regulated by PIAS1-mediated SUMOylation and the associated impacts on RNA modification, viral infection, and host defense." (PMID 38236021, 2024). "The efficacy of PIAS4 and PIAS1 function as intrinsic antiviral factor towards intracellular viral infection was investigated." (PMID 38590645, 2024). "To reveal the localization of NP and PIAS1 during virus infection, we performed immunostaining and confocal microscopy analysis." (PMID 35377920, 2022). "Expression changes in UPS genes identified in both ST_EPN_RELA and PF_EPN_B included several differentially expressed UPS genes associated with interferon gamma signaling (MID1, PIAS1, TRIM2, TRIM22, TRIM45) that may promote a proinflammatory milieu similar to that observed upon viral infections." (PMID 36293188, 2022). "A ligase within the PIAS family is responsible for the sumoylation of IRF3 and IRF7 observed after a viral infection, leading to the negative regulation of type I IFN gene expression, and PIAS1 is a mediator of IRF7 sumoylation." (PMID 33192313, 2020).
breast tumor (6 papers, 2014 to 2025). "Elevated PIAS1 expression was observed in breast tumor samples." (PMID 24586797, 2014). "Interestingly, in a PIAS1 TMA-based study of primary breast tumors, where correlation with patient survival data were not reported, PIAS1 was found to be increased in abundance in breast tumor-derived tissue." (PMID 28493978, 2017).
lung carcinoma (5 papers, 2015 to 2025). "Increasing evidence shows that PIAS1 is overexpressed in various human malignancies, including prostate and lung cancers." (PMID 32047143, 2020). "An overexpression of PIAS1 has been reported in lung cancer." (PMID 38590645, 2024). "The association between lung cancer and 4 target genes (FZD8, LRP5, PIAS1 andRUNX1) has been previously reported.It has been reported that FZD8is highly expressed in A549 cell line and the dysregulation of FZD8 might play key roles in human cancer through activation of beta-catenin-TCF pathway." (PMID 26642205, 2015).
B-cell lymphomas (4 papers, 2013 to 2023). "Furthermore, PIAS1-induced MYC sumoylation stabilizes MYC and facilitates MYC phosphorylation-associated transactivation in B-cell lymphomas." (PMID 35887358, 2022). "Furthermore, PIAS1-induced SUMOylation stabilizes MYC, and PIAS1 is implicated in facilitating transactivation-associated phosphorylation of MYC in B-cell lymphomas." (PMID 34503213, 2021). "It becomes apparent that PML is regulated by different molecules in different cancer types, e.g., by E6AP in B-cell lymphoma, CK2, and PIAS1 in NSCL cancer whereas KLHL20/Pin1 in prostate adenocarcinoma." (PMID 23730625, 2013).
colon cancer (4 papers, 2012 to 2019). "Therefore, reduced expression of PIAS1 is associated with colon cancer development." (PMID 31639157, 2019). "Our earlier work in breast and colon cancers found that knockdown of PIAS1 repressed CD44 expression." (PMID 29383121, 2017). "In colon cancer PIAS1 has been shown to repress the cancer stem cell population." (PMID 31639157, 2019). "To demonstrate that GATA4 and PIAS1 physically interact in mammalian cells, we performed coimmunoprecipitation experiments in HCT116 colon cancer cells by overexpressing HA epitope tagged GATA4 and FLAG epitope tagged PIAS1." (PMID 22539995, 2012).
Alzheimer disease (3 papers, 2021 to 2024). A progressive, neurodegenerative disease characterized by loss of function and death of nerve cells in several areas of the brain leading to loss of cognitive function such as memory and language. "Moreover, PIAS1 could exert neuroprotection in hippocampus of mice with Alzheimer’s disease through SUMOylation of HDAC1." (PMID 34857740, 2021). "However, the role played by PIAS1 in regulating neurodegenerative diseases, including Alzheimer’s disease (AD), has not been determined." (PMID 33759814, 2021).